ERBB2 (erb-b2 receptor tyrosine kinase 2)
Diseases named in the same sentence as ERBB2 in open-access papers (continued):
Sharing a sentence is not in itself a finding about the gene and the disease.
lymphoma (83 papers, 2003 to 2026). A malignant (clonal) proliferation of B- lymphocytes or T- lymphocytes which involves the lymph nodes, bone marrow and/or extranodal sites. "Our analysis identified over 1700 roles of HER2/ERBB2 in a wide range of diseases from brain injury/dysfunction to lymphomas, neoplasms, and carcinomas." (PMID 39409883, 2024). "Our data may have relevance for cancer biology, especially for B cell leukemia/lymphoma, multiple myleloma, and breast and other ErbB2-related cancers." (PMID 18159252, 2007). "None of the 6 normal lymph node and spleen samples or 42 lymphoma samples expressed detectable levels of MPL, ERBB2, or IGF1R mRNA." (PMID 21318160, 2010).
breast adenocarcinoma (81 papers, 2005 to 2025). "In order to determine potential mechanisms by which Pparγ1 coordinated the induction of growth factor and cytokine/chemokine signaling in ErbB2 tumors, we conducted genome wide PPARγ1 chromatin binding assays in human mammary adenocarcinoma cells." (PMID 33946495, 2021). "Ki-67 staining, a marker of cellular proliferation, demonstrated an increased percentage of Ki-67+ staining cells in the Pparγ1+/+ ErbB2 mammary adenocarcinoma." (PMID 33946495, 2021). "The ErbB2 and ErbB3 receptors showed remarkable co-localization in the three breast adenocarcinoma cell lines MCF-7, SK-BR-3, and BT-474." (PMID 34572289, 2021). "Similar chronic Morphine effects on ErbB signalling were also observed in ErbB2 overexpressing SKBR3 human mammary adenocarcinoma cells that carry endogenous κ-opioid receptors." (PMID 23308242, 2013). "Immunohistochemistry was used to compare relative expression levels of the hormone receptors ERα and PgR, cyclin D1, Ki67 and ErbB2 in the mammary adenocarcinomas that developed in the different genotypes across treatment groups." (PMID 24575359, 2012). "Mammary adenocarcinomas developed spontaneously in transgenic mice overexpressing ErbB2 (Her2)." (PMID 40884217, 2025). "Additionally, treatment of mice with trastuzumab and inhibition of I/II/IV HDAC by Penobinast promoted the NK-mediated response to HER2+ (also known as ERBB2+) breast adenocarcinoma." (PMID 38665224, 2024). "Moreover, similar results were obtained in human breast adenocarcinoma SK-BR-3 cells, which overexpress ErbB2 instead of EGFR." (PMID 36979639, 2023). "EphA2 is known to enhance ErbB2-induced mammary adenocarcinoma." (PMID 33946495, 2021). "However, recent investigations have now elegantly revealed the specific effects mediated by AKT1 and AKT2 isoforms in both the ErbB2-driven and the polyoma middle T (PyMT)-driven mammary adenocarcinoma transgenic mouse models." (PMID 29506489, 2018). "EphA2 physically and functionally interacts with ErbB2 to amplify Ras/mitogen-activated protein kinase (MAPK) and RhoA signaling in tumor cells, indicating that EphA2 cooperates with ErbB2/Neu to promote mammary adenocarcinoma tumorigenesis and metastatic progression." (PMID 25013485, 2014). "The antiproliferative action of the antibodies was analyzed in vitro, using two classical models of ErbB3-overexpressing breast adenocarcinomas: MCF-7 cells and SK-BR-3 cells, which also overexpress ErbB2." (PMID 34572289, 2021). "A similar switch in Heregulin-stimulated ERK1/2 signalling from an ErbB2-independent to an ErbB2-, PI3K- and metalloproteinase-dependent mechanism was also observed in κ-opioid receptor expressing SKBR3 human mammary adenocarcinoma cells." (PMID 23308242, 2013). "Hormone receptor, cyclin D1, Ki67 and ErbB2 expression were detected in all the mammary adenocarcinomas without any significant differences between genotypes or treatment groups." (PMID 24575359, 2012).
diabetes (79 papers, 2006 to 2026). "Beta-sitosterol was found to bind to ERBB2, a receptor tyrosine kinase linked to elevated levels that significantly correlate with a higher incidence of diabetes mellitus." (PMID 41141349, 2025). "Individuals with high ERBB2 levels exhibit a markedly increased risk of diabetes compared to those with lower levels." (PMID 41141349, 2025). "Evidences indicate that elevated levels of circulating ErbB2 are closely associated with increased incidence of diabetes." (PMID 35322023, 2022). "ErbB2 reduction after weight loss indicates that it participates in the vicious cycle of the pathophysiology of diabetes." (PMID 31815004, 2019). "These in vitro results support out findings in vivo and further imply that hyperglycemia associated with diabetes leads to elevation in ErbB2 expression and activity that ultimately mediates vascular dysfunction." (PMID 23826343, 2013). "This is not an unexpected finding as we showed above that diabetes is associated with reduced EGFR/erbB2 heterodimers and thus appear to be important signaling partners in cardiac function including following I/R injury." (PMID 22720029, 2012). "However, an important link of EGFR and diabetes has been identified before: elevated levels of ErbB2 are associated with hyperglycemia and impaired insulin sensitivity." (PMID 31815004, 2019). "Further, simple correction of hyperglycemia per se also does not completely prevent development of vascular complications in patients with diabetes implying that other factors associated with the diabetic state could induce ErbB2/EGFR/ERK1/2/ROCK signaling- a possibility that needs further study." (PMID 23826343, 2013). "Thus, our data suggest that strategies targeting ErbB2 may represent novel approaches for the treatment of vascular complications associated with diabetes." (PMID 23826343, 2013). "Recently, scholars have gradually paid attention to the relationship between ERBB2 and fibrosis, and they found that inhibition of HER2 can improve myocardial fibrosis caused by myocardial infarction or diabetes by regulating the TGF-β pathway." (PMID 36605402, 2022). "The importance of fatty liver was particularly striking among the top 30 diabetes-associated proteins (e.g. HGF, IGSF3, IL1RA, ALDH1A1, HNMT, ERBB2 and CDCP1)." (PMID 33279861, 2021). "As to the mechanism of diabetes-induced transactivation of ErbB receptors, high glucose-mediated ErbB2 transactivation occurred via a Src-dependent mechanism in VSMCs as evidenced by increased phosphorylation of Src at Y416." (PMID 34408653, 2021). "Multiple effects on insulin sensitivity, diabetic complications together with the anticancer efficacy point to the high potential of targeting both the MST and EGFR/ErbB2 axes for diabetes therapy." (PMID 31815004, 2019). "We had previously shown that diabetes-induced elevation in ErbB2 and subsequent downstream signaling via ROCK and ERK1/2 were involved in mediating vascular dysfunction in the mesenteric vascular bed." (PMID 26536590, 2015). "Transactivation of the epidermal growth factor receptor (EGFR or ErbB) family members, namely EGFR and ErbB2, appears important in the development of diabetes-induced vascular dysfunction." (PMID 26536590, 2015). "Acute AG825 administration (10−5 M) also opposed the diabetes-induced elevation in phosphorlated ErbB2 (Y1221/1222), ROCK II (Y256) and ERK1/2 in the isolated mesenteric vascular bed." (PMID 23826343, 2013). "Here, we report on the role of ErbB2 in mediating diabetes-induced vascular dysfunction in an experimental model of type 1 diabetes." (PMID 23826343, 2013). "Signaling studies confirmed that diabetes is associated with a reduction in EGFR and erbB2 phosphorylation at multiple tyrosine residues that appear to be important signalling cues for downstream effectors such as ERK1/2, p38MAP kinase and AKT." (PMID 22720029, 2012).
diabetes (continued). "EGFR/erbB2 signaling is an important cardiac survival pathway whose activation, particularly in diabetes, ischemia or following treatment with drugs that inhibit this cascade, significantly improves cardiac function." (PMID 22720029, 2012). "Further, EGF-mediated activation of EGFR/erbB2/AKT signaling in the hearts via modulation of FOXO3a activity appears to be a critical survival pathway in preventing diabetes-mediated cardiac dysfunction." (PMID 22720029, 2012). "Consistent with this, we showed that diabetes-led to an attenuation in EGFR/erbB2/AKT pathway that was further attenuated upon exposure of hearts to ischemia and correlated with a worsening recovery of cardiac function following I/R." (PMID 22720029, 2012). "Notably, higher ERBB2 expression was observed in unmarried patients (100%), pre-menopausal women (73–72%), and those with diabetes or hypertension, suggesting hormonal and metabolic modulation via PI3K/AKT/mTOR and MAPK/ERK pathways." (PMID 41403731, 2025). "MYH9, ERBB2, TCF4, VIM (vimentin), LRRK2 and CAV1 have been implicated as a principal mediator of diabetes mellitus." (PMID 36837510, 2023). "Fatty acid synthase (FASN) activity may partly account for the link between ErbB2 and diabetes because the overexpression of ErbB2 through a phosphatidylinositol 3'-kinase-dependent pathway promotes the expression of FASN29." (PMID 35322023, 2022). "This Fuels the idea that ErbB2 may be a bridge between diabetes and cancers, in that anti-diabetic agents may be a somewhat beneficial therapy for patients with cancer." (PMID 35322023, 2022). "Diabetes-induced vascular dysfunction arising from enhanced EGFR/ErbB2 signaling also led to downstream activation of FOXO3 (as evidenced by reduced phosphorylation at Ser253) through an AKT-independent manner that ultimately leads to apoptosis and vascular dysfunction." (PMID 34408653, 2021). "The results suggested that the exercise training against diabetes-induced hyperglycemia could be associated with an increase in insulin levels, a decrease in blood glucose, and adjustment of NRG1 and ErbB2 proteins." (PMID 32509881, 2020). "Thus, we showed that Ang-(1–7 inhibits ErbB2 transactivation induced by diabetes or high glucose as well as Ang II- or NE-mediated G-protein coupled receptor activation." (PMID 26536590, 2015). "Diabetes led to enhanced phosphorylation of ErbB2 at multiple tyrosine (Y) residues (Y1221/1222, Y1248, as detected by two different antibodies indicated as Y1248a and Y1248b, and Y877) that could be attenuated by AG825 treatment." (PMID 23826343, 2013). "Diabetes led to enhanced phosphorylation of ErbB2 at multiple tyrosine (Y) residues (Y1221/1222, Y1248 and Y877) in the MVB that could be attenuated by chronic AG825 treatment." (PMID 23826343, 2013). "However, the extent of cardiac dysfunction-induced by the inhibitors appeared to be greater in normal compared to diabetic hearts implying that the EGFR/erbB2 pro-survival pathway was significantly impaired in diabetes." (PMID 22720029, 2012). "We then asked whether ErbB-1 or ErbB-2 plays a role in the regeneration of beta cells and remission of diabetes in rAd-BTC-treated diabetic mice." (PMID 21897861, 2011). "Moreover, we prioritized drug-targets such as melatonin, resveratrol, eugenol, lapatinib, geldanamycin and azathioprine which interacted with ESR1, ERBB2, HSP90AB1 and RAC1, respectively and shown associations in diabetes treatment in experimental models of T1D." (PMID 33841528, 2020). "Thus, our data suggests that potential strategies aimed at modifying actions of signal transduction pathways involving ErbB2 pathway may prove to be beneficial in the treatment of diabetes-induced vascular complications." (PMID 23826343, 2013). "Thus, targeting of this novel ErbB2/EGFR-ERK1/2/ROCK pathway in diabetes-induced vascular complications might be clinically useful especially when there is already a vast experience with the use of ErbB2 inhibitors in several cancers." (PMID 23826343, 2013).
diabetes (continued). "In addition to the potential upstream of role of Ang II and other RAAS members, we speculate that diabetes and/or hyperglycemia might activate ErbB2 signaling via other, as yet, undefined pathways as well." (PMID 23826343, 2013). "Thus, potential strategies aimed at modifying actions of signal transduction pathways involving ErbB2 pathway may prove to be beneficial in treatment of diabetes-induced vascular complications." (PMID 23826343, 2013). "For example, diabetes enhances phosphorylation of EGFR1 and ErbB2, formation of EGFR/ErbB2 heterodimers and subsequent elevation in ERK1/2 and ROCK signaling leading to dysfunction in the mesenteric vasculature of T1DM rats." (PMID 34408653, 2021). "Diabetes mellitus increased the expression of protein levels of NRG1 and ErbB2 in skeletal muscles of STZ diabetic rats." (PMID 32509881, 2020). "The present research indicated that diabetes increased NRG1 and ErbB2 protein levels and rates of skeletal muscle fibrosis in STZ diabetic rats." (PMID 32509881, 2020). "In summary, results of the present study strongly suggested a mechanism under which the diabetes mellitus increased the fibrosis and NRG1/ErbB2 in skeletal muscles of STZ diabetic rats." (PMID 32509881, 2020). "We have previously shown the diabetes and/or hyperglycemia induces upregulation of EGFR and ErbB2 expression and phosphorylation that leads to vascular dysfunction via pathways involving ERK1/2, p38 MAPK and ROCKs." (PMID 26536590, 2015). "Ang II, and Aldosterone levels appear raised in diabetes and are also known transactivators of EGFR, and possibly ErbB2, via src and MMP-dependent mechanisms." (PMID 23826343, 2013). "Our results show for the first time that ErbB2 is an upstream effector of ROCKs and ERK1/2 in mediating diabetes-induced vascular dysfunction." (PMID 23826343, 2013). "For example, we have recently shown that signaling via ErbB2, in contrast to its detrimental role in vascular dysfunction described in the present study, may actually have a beneficial role in facilitating cardiac recovery from ischemia-reperfusion injury in diabetes." (PMID 23826343, 2013). "Here, we examined the role of ErbB2 (HER2/Neu), a transmembrane receptor tyrosine kinase of the ErbB/EGFR (epidermal growth factor receptor) family, in mediating diabetes-induced vascular dysfunction in an experimental model of type 1 diabetes." (PMID 23826343, 2013). "This study characterized the effects of diabetes and/or ischemia on epidermal growth factor receptor, EGFR, and/or erbB2 signaling pathways on cardiac function." (PMID 22720029, 2012). "Patients with diabetes (66% in both PCR assays) and hypertension (37% in first PCR, 100% in nested PCR) also showed elevated ERBB2 expression compared to those without these conditions." (PMID 41403731, 2025). "The reason why the exercise training decreased NRG1 and ErbB2 levels in soleus and EDL muscles may be due to the fact that it could significantly decrease blood glucose levels in the diabetes mellitus group." (PMID 32509881, 2020). "Similarly, the phosphorylation ratio of ERBB2 is higher and that of ERBB3 and ERBB4 is lower in mice with diabetes compared with controls." (PMID 28496106, 2017). "In this study, we hypothesised that ErbB2 is an upstream effector of ROCKs and ERK1/2 that its up-regulation leads to diabetes-induced vascular dysfunction in the mesenteric vascular bed." (PMID 23826343, 2013). "We initially assumed that diabetes might interrupt the expression level of NRG1 and ErbB2 proteins." (PMID 32509881, 2020). "Diabetes- or high glucose-mediated upregulation of ErbB2 phosphorylation was coupled with activation of Rho kinases (ROCKs) and ERK1/2 in MVB and in cultured vascular smooth muscle cells (VSMC) that were attenuated upon treatment with either chronic or acute AG825 or with anti-ErbB2 siRNA." (PMID 23826343, 2013).
diabetes (continued). "As to what might be the precise upstream inputs and downstream effectors of this novel ErbB2/EGFR-ERK1/2-ROCK pathway in mediating diabetes-induced vascular dysfunction are not clear." (PMID 23826343, 2013). "However, recent data from our laboratory showed that specific inhibition of ErbB2 receptor with AG825 or siRNA had similar vascular effects as a dual EGFR/ErbB2 inhibitor implying that ErbB2 rather than EGFR may be the predominant signaling pathway involved in diabetes-induced vascular dysfunction." (PMID 26536590, 2015). "Western blotting analyses showed that hearts isolated from STZ-induced diabetes, but not exposed to I/R, exhibited significantly reduced phosphorylation of EGFR and erbB2 at multiple tyrosine (Y) residues." (PMID 22720029, 2012).